HAT1 (histone acetyltransferase 1)
Diseases named in the same sentence as HAT1 in open-access papers (continued):
Sharing a sentence is not in itself a finding about the gene and the disease.
colitis (1 paper, 2026). Inflammation of the colon. "Conversely, genetic ablation of TRIP13 substantially reversed the effects induced by HAT1 overexpression, including enhanced Treg expansion and attenuation of colitis." (PMID 41535263, 2026). "Mechanistically, TNFR2 signaling elevated TRIP13 expression, which stabilized HAT1 protein by preventing UBE4A-mediated polyubiquitination degradation of HAT1, thus promoting Treg proliferation and protecting against colitis." (PMID 41535263, 2026). "TRIP13 knockout markedly reversed the effects of HAT1 overexpression on Treg expansion and the progression of colitis." (PMID 41535263, 2026). "Conversely, genetic ablation of TRIP13 substantially reversed the effects induced by HAT1 overexpression, including enhanced Treg expansion and attenuation of colitis, suggesting that TRIP13 is required for HAT1-mediated functions." (PMID 41535263, 2026). "In a mouse colitis model, TRIP13 overexpression markedly alleviated colon inflammation by enhancing Treg expansion, an effect that was reversed by HAT1 knockdown." (PMID 41535263, 2026).
histiocytic sarcoma (1 paper, 2019). An aggressive malignant neoplasm with a poor response to therapy, usually presenting as stage III/IV disease. "The most striking finding in the liver and spleen of Hat1+/− mice was the presence of histiocytic sarcoma in a high percentage of these animals (50% and 33%, respectively)." (PMID 31290578, 2019).
Huntington disease (1 paper, 2019). Huntington disease (HD) is a rare neurodegenerative disorder of the central nervous system characterized by unwanted choreatic movements, behavioral and psychiatric disturbances and dementia. "An interesting finding of this study is that reduced Hat1 ameliorates retinal neurodegeneration in a Drosophila model of Huntington’s Disease." (PMID 31784689, 2019).
leiomyoma (1 paper, 2024). A well-circumscribed benign smooth muscle neoplasm characterized by the presence of spindle cells with cigar-shaped nuclei, interlacing fascicles, and a whorled pattern. "In comparison with leiomyoma, leiomyosarcoma had greater levels of HAT1 expression." (PMID 38410101, 2024).
male infertility (1 paper, 2025). The inability of the male to effect fertilization of an ovum after a specified period of unprotected intercourse. "By unraveling the spatiotemporal and molecular dynamics of Hat1, our findings lay the groundwork for future investigations into the epigenetic basis of male fertility and potential therapeutic targets for male infertility." (PMID 41282984, 2025).
medulloblastoma (1 paper, 2022). A malignant, invasive embryonal neoplasm arising from the cerebellum. "The RNA-seq results from Fsmo;hGFAP-Cre medulloblastomas showed significant downregulation of histone acetyltransferases (HAT: Hat1 and Kat2a/GCN5), the histone deacetylase (HDAC) Hdac1, and the histone acetylation reader Brd2 between vehicle- and LDE-treated samples." (PMID 36688010, 2022).
meningioma (1 paper, 2025). A generally slow growing tumor attached to the dura mater. "In addition, aptamer apHAT610 is a promising tool, superior to monoclonal antibody diagnostics, in aptahistochemistry of meningiomas overexpressing histone acetyl transferase-1 (HAT1), which are among the most aggressive meningiomas, with poor prognosis and higher rates of early relapse." (PMID 41012445, 2025).
metastatic melanoma (1 paper, 2023). A melanoma that has spread from its primary site to another anatomic site. "The reduction of HAT1 expression in metastatic melanoma caused the development of the v-raf murine sarcoma viral oncogene homolog B1 (BRAF) inhibitors’ resistance, such as vemurafenib and dabrafenib, kinase inhibitors targeting BRAFV600E in melanoma cells." (PMID 37048148, 2023). "The lower expression of HAT1 was observed also in metastatic melanoma, correlating with a resistance to the treatment." (PMID 37048148, 2023).
osteoarthritis (1 paper, 2021). A noninflammatory degenerative joint disease occurring chiefly in older persons, characterized by degeneration of the articular cartilage, hypertrophy of bone at the margins and changes in the synovial membrane. "Several chromatin modifying enzymes such as HAT1, KAT5, HDAC6, MBD1, and DNMT3A were downregulated at gene expression level in women with post-menopausal osteoporosis and osteoarthritis, with superior quantity and quality of bone being directly associated with HAT1, HDAC6, and MBD1 expression." (PMID 33805567, 2021).
sterility (1 paper, 2022). "The present results suggest that the decreased level of HAT1 and increased level of HDAC1 may result in the decreased H3K9 acetylation in cattle-yaks and might be associated with their sterility." (PMID 36009610, 2022).
systemic candidiasis (1 paper, 2015). "Nonetheless, although showing increased persistence in the host, deletion of HAT1 strongly attenuates virulence in a mouse model of systemic candidiasis." (PMID 26473952, 2015).
uterine leiomyosarcoma (1 paper, 2024). "Researchers investigating the potential therapeutic benefits of uterine leiomyosarcoma have discovered that a combination of Pazopanib and heat inhibits the production of histone acetyltransferase 1, which in turn inhibits the growth of uterine leiomyosarcoma (HAT1)." (PMID 38410101, 2024).
cancer (32 papers, 2012 to 2026). A tumor composed of atypical neoplastic, often pleomorphic cells that invade other tissues. "However, HAT-1 seemed to present the clearest relationship between its expression and cancer mortality, with a hazard risk of 21.74." (PMID 38785507, 2024). "Furthermore, this increase in HAT1 levels is associated with poor prognosis, tumor differentiation, and survival of cancer patients." (PMID 36612223, 2022). "Moreover, a recent study reported that loss of HAT1 was involved in drug resistance in cancer treatment." (PMID 34323404, 2021). "Altogether, these findings suggested that HAT1 transcriptionally regulate PD-L1 expression in cancer settings, and implicated that targeting HAT1 activity could be used as a therapeutic approach for cancer treatment." (PMID 32760400, 2020). "Moreover, HAT1 is overexpressed in multiple types of cancer and associated with poor prognosis." (PMID 30709380, 2019). "HAT1, a key enzyme essential for clonogenicity and frequently upregulated in cancers such as HeLa, was significantly downregulated by fisetin, accompanied by a dose-dependent reduction in overall HAT activity." (PMID 41562705, 2026). "Collectively, these findings indicate that HAT1 exerts immunomodulatory function by controlling Treg infiltration in cancer." (PMID 41535263, 2026). "HAT1, which is important for achieving clonogenicity and is frequently upregulated in many cancers, including HeLa cells." (PMID 40159638, 2025). "In their quantitative proteomic analysis of HepG2 cancer cells, Yang and colleagues discovered that HAT1 coordinates the succinylation of a wide array of proteins, including histones and non-histone proteins." (PMID 39278916, 2024). "The succinylation of PGAM1 by HAT1 seems to play a critical role in promoting tumor progression in vitro and in vivo in various types of cancer, including PDAC." (PMID 38785507, 2024). "In this review, we report an update of the biological functions of HAT1 and its involvement in carcinogenesis, highlighting its potential role as a biomarker for cancer." (PMID 37048148, 2023). "Immunohistochemical analysis of this rare cancer revealed that HAT1 is expressed more than in leiomyomas, a benign smooth muscle tumor." (PMID 37048148, 2023). "HAT1 expression levels, divided by upregulation or downregulation, and functions in different types of cancer." (PMID 37107673, 2023). "In this review, we summarize and update the current knowledge about the biological function of this acetyltransferase, highlighting recent advances of HAT1 in the pathogenesis of cancer." (PMID 37048148, 2023). "Several studies highlight a specific role for HAT1 in regulating molecular pathways, which are altered in several pathologies, among which is cancer." (PMID 37048148, 2023). "Collectively, these studies support an immunomodulatory role for HAT1 in cancer, making HAT1 an important player to study in carcinogenesis." (PMID 37107673, 2023). "In this context, HAT1 participates in DNA damage repair, telomeric silencing and other hallmarks of cancer." (PMID 37107673, 2023). "Particularly, HAT1-mediated succinylation regulates gene expression in cancer, contributing to cancer initiation and progression." (PMID 37048148, 2023). "Histone acetyltransferase 1 (HAT1) has attracted increasing interest as a potential therapeutic target due to its involvement in multiple pathologies, including cancer." (PMID 36612223, 2022). "Although the real relevance of this enzyme in cancer remains to be determined, for which more studies are needed, the available data are sufficient to indicate that HAT1 can be considered as a potential therapeutic target." (PMID 36612223, 2022). "In the process of chromatin assembly, HAT1 participates in the acetylation of newly synthesized histone H418, 19 and is scarcely understood in cancer research." (PMID 34323404, 2021).
cancer (continued). "HAT1 is also a transcription factor that upregulates the expression of various genes such as Bcl2L12 and Fas, and promotes cancer cell proliferation." (PMID 34880761, 2021). "It has been reported that HAT1 functions as a transcription factor to regulate the expression of various genes, such as Bcl2L12 and Fas, and modulates cancer cell proliferation, apoptosis and metabolism." (PMID 30709380, 2019). "Strikingly, HAT1 was involved in the cancer immunity response by regulating the PD-L1 expression, and this process was mainly mediated by BRD4." (PMID 30709380, 2019). "In particular, we demonstrated that HAT1 functioned as an important regulator in cancer immunity via transcriptionally upregulating the PD-L1 level in tumor cells." (PMID 30709380, 2019). "The relevance of HAT-1 in cancer has been consistently demonstrated in the available literature." (PMID 38785507, 2024). "Furthermore, their investigations revealed that HAT1 is capable of H3K122succ, subsequently promoting favorable gene expression patterns within cancer cells." (PMID 39278916, 2024). "Moreover, lower histone H4K5/K12 acetylation, due to decreased HAT1 activity, induces dysregulated epithelium regeneration, contributing to a greater incidence of cancer." (PMID 37048148, 2023). "Furthermore, alterations in HAT1 molecular mechanism correlate with the deregulation of several biological processes, thus promoting cancer onset." (PMID 37048148, 2023). "HAT1 is also involved in cancer immunity through this regulation of PD-L1 expression." (PMID 37513949, 2023). "Furthermore, a different expression of HAT1 has been highlighted in some types of human cancer, suggesting the controversial role of this protein both as an oncogene and as a tumor suppressor." (PMID 37048148, 2023). "This differential effect is also known as the “butyrate paradox”, and could be explained by the role of butyrate as an HDAC inhibitor in cancer cells and as an activator of histone acetyltransferase 1 (HAT1) in normal cells." (PMID 37185889, 2023). "HAT1 is also involved in other critical events related to cancer development and progression." (PMID 37107673, 2023). "Previous studies indicate that HAT1 regulates cancer immunity." (PMID 37513949, 2023). "Also, HAT1 is found to be elevated in several cancers and consequently, HAT1-mediated succinylation was found to be involved in tumour progression." (PMID 38213532, 2023). "HAT1 may also have a role in the pharmacological response to different cancers; in this case, its action may also have a controversial role." (PMID 37048148, 2023). "The fact that high levels of this protein are observed in cancer may be due to its involvement in different cellular functions during the replication phase when the cell has high levels of HAT1." (PMID 36612223, 2022). "Histone acetyltransferase 1 (HAT1) succinylated histone H3 at K122, which could provide epigenetic and gene expression regulation in cancer cells." (PMID 36010594, 2022). "Additionally, HAT1 functions as a transcription factor in cancer cells and regulates the expression of various genes, including Fas and Bcl2L12,24, 28, 29 to promote lung and nasopharyngeal cancer cell proliferation, apoptosis, and metabolism." (PMID 34323404, 2021). "HAT1 was previously reported to interact with HIF2A, promoting its stability by acetylation in cancer cells." (PMID 41535263, 2026). "Recent studies illustrate that desuccinylase (e.g., SIRT5 and SIRT7) and succinyltransferase (e.g., KAT2A, CPT1A, HAT1, and alpha-KGDH) expression and malfunction are strongly related to immune escape of cancer." (PMID 40865948, 2025). "In conclusion, our research reveals that HAT1-regulated RPA1 lactylation plays an important role in homologous recombination and radioresistance, suggesting that HAT1 may become a potential therapeutic target for reversing the radioresistance caused by lactate accumulation in cancer cells." (PMID 41271679, 2025).
cancer (continued). "Recently, Hou, et.al conducted RNA sequencing of HepG2 cancer cells treated with Bevacizumab and found that Bevacizumab triggers cancer cells ferroptosis through the VEGF/PI3K/HAT1/SLC7A11 axis." (PMID 40670757, 2025). "Histone acetyltransferase 1 (HAT1) is one of the upstream mediators of PVT1, which determines the cancer cells’ resistance to gemcitabine." (PMID 38559560, 2024). "Knocking out HAT1 in a nude mice tumorigenicity model reduced H3 K122 succinylation and inhibited the growth of HepG2 and PANC1 cancer cells, suggesting that H3 K122 succinylation is important for tumourigenesis." (PMID 38213532, 2023). "Furthermore, it is worth mentioning that HAT1 and KAT2A were highly expressed in advanced TNM stages, suggesting the expression of these signature genes may be associated with advanced-stage and high-grade carcinomas of LIHC." (PMID 37763801, 2023). "Collectively, all these results strongly indicate that HAT1 serves as an oncoprotein in PCa and CRPC and promotes cancer cell proliferation both in vitro and in vivo." (PMID 34323404, 2021). "Therefore, HAT1 might regulate cancer cell proliferation via PD-L1." (PMID 30709380, 2019). "The regulation of the expression and activity of succinyltransferases, including α-KGDHC, KAT2A, HAT1, CPT1A, OXCT1, and p300, enables cancer cells to alter the function and stability of proteins, which, in turn, affects cell proliferation, invasion, and metastasis." (PMID 39781339, 2025). "For example, histone acetyltransferase 1 (HAT1), a type B histone acetyltransferase, that succinylated histone H3 on K122, has been reported to contribute to epigenetic regulation and gene expression in cancer cells." (PMID 34788852, 2022). "The data show that the activation of PAR2 suppresses expression of HAT1 in lung epithelial cells, indicating that factors activating PAR2 may suppress Fas expression and contribute to the pathogenesis of cancer." (PMID 29163803, 2017). "Also, targeting each of HAT1, PVT1, miR-619-5p, and EZH2 individually or in combination may enhance the cancer cells’ resistance to gemcitabine and increase the effects of chemotherapy and prognosis in patients." (PMID 38559560, 2024). "Very recently, histone acetyltransferase 1 (HAT1) was demonstrated to modulate lysine succinylation on various proteins including histones and non-histones, and HAT1 succinylates histone H3 on K122 (H3K122), which contributes to epigenetic regulation and gene expression in cancer cells." (PMID 35547393, 2022). "For non-histones, HAT1 catalyzes the succylation of the glycolytic enzyme phosphoglycerate mutase 1 on K99 in tumor cells, resulting in increased enzymatic activity and stimulation of glycolysis flux in cancer cells." (PMID 36397343, 2022). "Similarly, HAT1 (histone acetyltransferase 1), which succinylates H3K122, contributing to epigenetic gene regulation in cancer cells and PGAM1 (Phosphoglycerate Mutase 1) in a non-histone region, stimulates glycolytic fluxes in cancer cells." (PMID 35631199, 2022).